SIRT6 (sirtuin 6)
Diseases named in the same sentence as SIRT6 in open-access papers (continued):
Sharing a sentence is not in itself a finding about the gene and the disease.
cancer (continued). "ST6GalNac2, known to have a role in cancer, also appears to be upregulated in the presence of overexpressed SIRT6 in HUVEC-SIRT6 samples." (PMID 36982232, 2023). "In vitro and in vivo studies have indicated the contrasting roles of SIRT6 in cancer; it acts either as a tumour suppressor or promoter in a context-specific manner." (PMID 37958565, 2023). "In this scenario numerous studies on Sirt6 null and transgenic models have endowed this sirtuin with both anti-aging and anti-cancer properties." (PMID 38081972, 2023). "Studies on mice with the SIRT6 knockout gene reported increased defects in DNA repair, a shortened lifespan, and a higher cancer incidence." (PMID 37630770, 2023). "In this Review, we first describe the general functions of SIRT6, except those in cancer, and then summarize the recent progress in understanding the specific functions of SIRT6 in the retina and RPE." (PMID 38016059, 2023). "In vitro studies showed that this compound induced inhibition of the cell cycle in the G0/G1 phase, which confirms that the activation of SIRT6 inhibits cell cycle progression in cancer cells." (PMID 38203666, 2023). "Although SIRT6 has emerging potential as a therapeutic target in cancer, few small molecule inhibitors of SIRT6 have been identified to date, and most of these inhibitors show weak inhibitory activity against SIRT6 and limited antitumor activity." (PMID 37542062, 2023). "Since oxidative stress mechanisms favor cancer cell survival, SIRT6 was reported to be involved in regulating oxidative stress mechanisms." (PMID 38235110, 2023). "For example, UBCS039 induces deacetylation of Sirt6-targeted histone H3 sites in human cancer cells." (PMID 36490326, 2022). "In summary, SIRT6 has shown contradictory results, promoting or suppressing cancer among different cancers, and even at different stages of development or different cell lines of the same cancer." (PMID 35463332, 2022). "On the other hand, most evidence regarding SIRT6 demonstrates action as a tumor suppressor and is downregulated in many cancers." (PMID 36225477, 2022). "We investigated the effects of SIRT6 on protein kinase C activator- and cytokine-mediated cancer cell invasion and migration in MCF-7 and MDA-MB-231 cells and the association between SIRT6 and matrix metalloproteinase-9 (MMP-9) expression." (PMID 35840633, 2022). "Conversely, some researchers maintain that the SIRT6 allosteric activator can inhibit the proliferation of cancer cells." (PMID 35915188, 2022). "On silencing SIRT6 with its siRNA, there was a decrease in mitochondrial fragmentation along with reduced cancer cell migration and invasion." (PMID 35686673, 2022). "Increasing SIRT6 levels represses survivin and inhibits cancer progression by reducing histone H3K9ac and NF-κB activation." (PMID 35463332, 2022). "In this report, we have focused on a crucial enzyme of the sirtuin family SIRT6, whose role in cancer progression has been conflicting in different cancer types." (PMID 35686673, 2022). "We suggest that RV directly modulates PPARα-mediated L1-RTP in somatic cells and that MAPK signaling closely interacts with SIRT6 preventing human diseases, such as cancer and sporadic cases of inborn errors." (PMID 35546166, 2022). "This review focuses mainly on the regulatory functions of SIRT6 in aging, cancer, and, especially, immunity." (PMID 35463332, 2022). "Considering the transcriptomic data obtained, we focused on the involvement of SIRT6 in cancer and metabolism." (PMID 35686673, 2022). "SIRT6 deacetylates the promoter of Bax (the main determinant of apoptosis of cancer cells) at H3K9 and suppresses its promoter activity to prevent cancer cell apoptosis." (PMID 35463332, 2022). "The analysis of clinical research showed that patients with lower SIRT6 levels tend to have larger tumor sizes and more advanced cancer staging." (PMID 36499440, 2022).
cancer (continued). "So SIRT6 is involved in cancer regulation is obvious.In addition, large amounts of data indicate that SIRT6 is directly involved in the occurrence and development of cancer." (PMID 35463332, 2022). "SIRT6 plays important roles in the regulation of cancer cell metabolism and the promotion of cancer cell apoptosis." (PMID 36010594, 2022). "When the data from the TCGA dataset was compared to normal tissue, it was discovered that SIRT6 expression was significantly different in 11 different types of cancers." (PMID 35172823, 2022). "Resveratrol is a better activator of SIRT6 in drug-sensitive LoVo cells, which corresponds to its greater anti-cancer properties in these cells." (PMID 35326523, 2022). "Mechanistically, SIRT6 overexpression induces E-cadherin degradation to improve cancer invasion and migration ability." (PMID 35463332, 2022). "Against this background, SIRT6 is considered to be a regulator in the progression of cancer and thus affect the survival rate of cancer patients." (PMID 35172823, 2022). "Here we show that celastrol increases SIRT6 expression in both sensitive and CSCs-like cells, which correlates well with its anti-cancer effects." (PMID 35326523, 2022). "More recently, its metabolic regulatory functions have been shown to be important in cancer as well, with Sirt6 functioning as a tumor suppressor in mouse models and human patients in both colorectal and pancreatic adenocarcinoma." (PMID 35834102, 2022). "On the other hand, SIRT6 is thought to play a role in or suppress the progression of several types of cancer." (PMID 35172823, 2022). "Depending on the different cancer type, or even on the different cancer stage, SIRT-6 has been reported to act as an oncopromoter or oncosuppressor." (PMID 36080416, 2022). "In the same cancer model, SIRT-6 inhibitors identified by a VS (see Section 3.6), having a quinazolinedione and salicylate-like structure, reduced proliferation and increased sensitivity to gemcitabine." (PMID 36080416, 2022). "Specifically, histone deacetylation activity of SIRT6 protects against abnormal telomere metabolism which is characteristic of cancer cells." (PMID 36225477, 2022). "Considering this background information, we tried to explore the possible metabolic and bioenergetic alterations manifested by SIRT6 in promoting the invasiveness of cancer cells." (PMID 35686673, 2022). "Studies have revealed that dysregulation of SIRT6 activity leads to the onset and development of many diseases, including but not limited to metabolic diseases, cardiovascular diseases (CVDs), cancers and neurodegenerative diseases." (PMID 36465178, 2022). "Sirtuin 6 (SIRT6), a DNA repair-related gene, has undergone an extremely thorough study for its involvement in the development of many different cancers." (PMID 35251169, 2022). "Taken together, the data presented in this study suggest that SIRT6 has the ability to modulate multiple targets to block cancer‐induced cachexia." (PMID 34212132, 2021). "Other activators of SIRT6 have the biological function of anti-cancer, while the potential effect of these activators in CVDs needs further studies." (PMID 33855020, 2021). "Through histone deacetylation at diverse target genes, SIRT6 is a central regulator of transcriptional programs in aging, cellular metabolism, and cancer biology." (PMID 34573442, 2021). "In HepG2 cells, SIRT6 overexpression impairs cancer proliferation through the inhibition of ERK1/2 signaling and promotes apoptosis by inducing increased levels of cleaved caspase-3." (PMID 33800266, 2021). "Our findings also uncover a new mechanism of SIRT6 in suppressing metastatic cancer cell phenotypes and identify acetyl-CoA responsive cell migration and adhesion genes as downstream targets of SIRT6." (PMID 34573442, 2021). "SIRT6 suppresses cell proliferation through Twist1, and it also regulates metabolic cancer cell reprogramming through GLUT1." (PMID 33920726, 2021).
cancer (continued). "SIRT6, through its deacetylation activity, regulates Bax, which is the primary pathway involved in the apoptosis of cancer cells." (PMID 33920726, 2021). "We therefore examined the effects of SIRT6 on the invasive properties of cancer cells using several independent assays and cancer cell types." (PMID 34573442, 2021). "For example, SIRT6 suppressed cancer stem-like capacity in tumors with PI3K activation independent of its deacetylase activity." (PMID 34927546, 2021). "In exploring a potential functional interaction of SIRT6 with ACLY, we were surprised to observe that ACLY protein levels were consistently elevated in SIRT6-deficient cancer cells." (PMID 34573442, 2021). "These fatty acid derivatives are expected to upregulate the SIRT6 activity, and therefore can be used as a therapeutic target for inflammation and cancer." (PMID 33920726, 2021). "In osteosarcoma cell lines, SIRT6 knock-down has been shown to potentiate the effect of conventional chemotherapeutics inducing block of cancer cell proliferation and cell death." (PMID 33800266, 2021). "In the context of cancer, SIRT6 was considered as a double−edged sword due to its dual role of both tumor suppression and promotion, depending on the type of tumors." (PMID 33855020, 2021). "Notably, SIRT6 is also implicated in cancer cell migration and metastasis; however, controversy remains over whether it promotes or prevents these processes, with conflicting reports from studies involving different cancer cell types." (PMID 34573442, 2021). "This study provides important insights into the crosstalk between SIRT6 activity and cancer cell proliferation." (PMID 33800266, 2021). "Our findings uncover a novel mechanism of SIRT6 in suppressing invasive cancer cell phenotypes and identify acetyl-CoA responsive cell migration and adhesion genes as downstream targets of SIRT6." (PMID 34573442, 2021). "As shown in this study, Sirt1 is likely to aggravate malignant development: we observed an increase in ROS expression, leading to an elevated frequency of cancer cell death, when Sirt1 was downregulated by Sirt6." (PMID 33727672, 2021). "In the following sections, we discuss the most relevant SIRT6 activators and inhibitors that have been indicated to impact cancer progression and cell death so far." (PMID 33800266, 2021). "Future studies should address this possibility as a way to identify metabolic liabilities of cancer cells with low SIRT6 expression or in which SIRT6 is pharmacologically inhibited." (PMID 33482921, 2021). "Among these, a study on the phosphorylation of SIRT6 has focused on its important roles in cancer progression." (PMID 34359939, 2021). "One of the key regulators of these pathways is the epigenetic enzyme SIRT6, which has been shown to have a dichotomous function in cell fate determination and, consequently, cancer initiation and progression." (PMID 33800266, 2021). "Novel insights about the oncogenic role of SIRT6 in HCC indicated that the SIRT6-mediated activation of the ERK1/2 pathway can promote cancer cell proliferation and invasion." (PMID 33800266, 2021). "As a NAD+ dependent histone deacetylase, SIRT6 plays key roles in the regulation of metabolism, inflammation, longevity, genome stability and cancer." (PMID 33869219, 2021). "SIRT6 has been found to modulate the expression of both pro- and anti-apoptotic factors, thus influencing cell survival and affecting cancer development in a context-dependent manner." (PMID 33800266, 2021). "Conversely, the dual role of SIRT6 in cancer, cell survival and inflammation has also motivated the development of SIRT6 inhibitors." (PMID 33800266, 2021). "This study indicates that excessive autophagy stimulation is lethal for cancer cells and paves the way for therapies based on pharmacological activation of SIRT6 to exploit this mechanism." (PMID 33800266, 2021). "An increasing number of studies reported an altered expression of SIRT6 in cancer, both at gene and protein levels." (PMID 33800266, 2021).
cancer (continued). "Consistent with our findings, SIRT6 functioned as an anti-oncogene in CRC through inhibiting cancer stem cell proliferation." (PMID 33510943, 2021). "Accumulating evidence has emerged to suggest that SIRT6 can boost the apoptosis of diverse cancer cells." (PMID 34927546, 2021). "Due to the role played by SIRT6 in the regulation of cellular homeostasis, mounting evidence points towards its involvement in cancer." (PMID 33800266, 2021). "Among all, Sirt1, Sirt6 and Sirt7 was demonstrated to involve in DNA damage repair, the over-activation of which accounts mainly for radioresistance of cancer 19,20." (PMID 34405009, 2021). "Our results demonstrate dual benefits of muscle‐specific moderate over‐expression of SIRT6 in a mouse model of cancer‐cachexia." (PMID 34212132, 2021). "In this cancer model, SIRT6 restoration led to apoptosis through upregulation of Bax and cleaved caspase-8, along with downregulation of Bcl-2 and inhibition of the JAK2/STAT3 pathway." (PMID 33800266, 2021). "The effects of SIRT6 on cancer biology are regulated by its phosphorylation status, especially on Ser338." (PMID 34359939, 2021). "Similar to Sirt6 and Sirt7, Sirt3 was also related to DNA damage repair signaling pathway, which is one of core mechanism of cancer radioresistance." (PMID 34405009, 2021). "SIRT6 overexpression was shown to augment FoxO3a levels, reducing the levels of glycolytic genes and cancer cell proliferation." (PMID 33800266, 2021). "A possible explanation is that SIRT6 overexpression is selectively toxic to multiple cancer cells, and there are multiple ways to fine-tune SIRT6 levels in cancer cells in response to stress conditions." (PMID 34702956, 2021). "SIRT6 is a member of the sirtuin family and has diverse roles in normal physiology and cancer biology, including aging, cell metabolism, proliferation, the invasiveness of cells, and DNA damage repair." (PMID 34359939, 2021). "Researchers in South Korea led by Sang Yoon Kim and Seong Who Kim at the University of Ulsan, Seoul, investigated the role of the proteins Sirt6, Sirt1 and MDM2 in controlling the death of cancer cells caused by chemicals called reactive oxygen species (ROS)." (PMID 33727672, 2021). "On the other hand, studies have also shown SIRT6 to enhance cancer metastasis by promoting EMT in lung, thyroid, and liver cancer." (PMID 34702956, 2021). "Sirt6-induced cell death was substantially suppressed upon inhibition of MDM2, indicating that MDM2 plays an essential role in Sirt6-related cancer cell death." (PMID 33727672, 2021). "The role of SIRT6 in DNA damage repair enables cancer cells to be refractory genotoxic anti-cancer therapeutics." (PMID 34359939, 2021). "Analysis of publicly available cancer microarray databases validated that Sirt6 was upregulated in DLBCL and correlated with shorter overall survival." (PMID 32711549, 2020). "Despite the roles of SIRT6 as a sensor to repair DNA damage, higher expression of SIRT6 is related to increased proliferation and invasiveness of cancer cells." (PMID 33198792, 2020). "Conversely, SIRT3 and SIRT6 also act as tumor suppressors, restricting aerobic glycolysis in cancer cells through destabilization of hypoxia inducible factor 1 subunit alpha (HIF-1α) and inhibition of glycolytic kinases, respectively." (PMID 33117804, 2020). "Dysregulation of sirtuin 6 has a strong impact in various diseases including dysmetabolism, neurodegeneration, diabetes, and cancer." (PMID 33396307, 2020). "In addition, when considering the reports that elevated expression of SIRT6 is associated with poor prognosis of human cancers, agents which block the DNA damage repair pathway might be useful for the treatment of other human cancer expressing high levels of SIRT6." (PMID 33198792, 2020).
cancer (continued). "Regarding a role for SIRT6 as an oncogenic molecule, SIRT6 stimulated the proliferation of cancer cells by stimulating the Wnt/β-catenin pathway." (PMID 33198792, 2020). "Recently, there are increasing reports focusing on the roles of the sirtuins, especially on SIRT6, in human cancers." (PMID 33198792, 2020). "In this study, we performed a meta-analysis of nine studies including 867 cancer patients and found that high expression of SIRT6 was significantly related to longer OS time in gastrointestinal cancers including CRC, GC, PDAC, and HCC." (PMID 33335996, 2020). "Concerning SIRT6, it is downregulated in several cancers, including hepatocellular carcinoma, but it is overexpressed in breast cancer and NSCLC." (PMID 32344886, 2020). "The importance of SIRT6 to DNA maintenance is exemplified in SIRT6-KO mice phenotypes, which include accelerated ageing, cancer and neurodegeneration." (PMID 31995034, 2020). "Consistently, the expression of SIRT6 was elevated in cancers compared with normal counterpart cells in the colon, esophagus, melanocytes, thyroid, and lymph node." (PMID 33198792, 2020). "SIRT6 has important roles in physiological and pathological processes, regulating aging, cancer, obesity, insulin resistance, inflammation, and energy metabolism." (PMID 32736564, 2020). "Although the role of SIRT6 in tumorigenesis and development still have many unanswered questions, SIRT6 would be utilized for cancer prevention and site-specific treatment, especially for cancer nanomedicine." (PMID 33335996, 2020). "The expression of SIRT4 and SIRT5 were down-regulated in cancer tissues, while SIRT6 and SIRT7 were up-regulated." (PMID 32158696, 2020). "Various studies have demonstrated that SIRT6 can deacetylate several cancer-related genes, such as PKM2, NF-κB, HIF1α, CtBP, and JUN, which results in a reduction in cell proliferation." (PMID 31817470, 2019). "SIRT6 overexpression increases cancer cell proliferation by directly modulating oncogenic proteins or the acetylation of H3K9 and H3K56 of oncogene promoter dependent on its deacetylase activity." (PMID 31842909, 2019). "Sirt6 promotes longevity in male mice, and it suppresses aging phenotypes and induces apoptosis in cancer cells." (PMID 31844103, 2019). "The results of this work showed that increasing the level of SIRT6 or targeting the anti-apoptotic activity of survivin at the initiation stage markedly impairs cancer development." (PMID 31591350, 2019). "In fact, recent studies have proven that SIRT6 plays an important role in cancer related cellular pathways and processes such as metabolism, genome stability, cellular proliferation and apoptosis, inflammation and immunocompetence." (PMID 31591350, 2019). "Sirt6 activation protects against metabolic and aging-related diseases, and Sirt6 inhibition is considered a cancer therapy." (PMID 31844103, 2019). "On the other hand, SIRT6 is overexpressed in some cancers, such as squamous cell carcinoma (SCC), breast cancer, ovarian cancer and multiple myeloma, suggesting it possesses oncogenic activity." (PMID 31842909, 2019). "This further suggests that SIRT1 and SIRT6 cooperate to set a threshold for FOXO3 acetylation in the cancer cells." (PMID 31357743, 2019). "SIRT6 is one of the mammalian sirtuins that have gotten the most interest in several studies in recent years, and through its effects on histone deacetylation, SIRT6 protects against aging and age-related diseases, as among which cancer." (PMID 31591350, 2019). "This review addresses the sirtuins role in cancer pathophysiology, with a special interest of the SIRT6 action in different kinds of cancers, as well as the first efforts in SIRT6 modulators research." (PMID 31591350, 2019). "The recent evidence of the role of SIRT6 in carcinogenesis is also discussed, focusing on the potential use of SIRT6 modulators in cancer nanomedicine." (PMID 31591350, 2019).